RNY4P28 (RNY4 pseudogene 28)
Gene: Miscellaneous RNA gene on chromosome 13 (60,187,738 to 60,187,830, reverse strand). Ensembl gene ENSG00000202151.
Homologues: Orthologues: chimpanzee Y_RNA (100% identical), macaque Y_RNA (96% identical), dog Y_RNA (86% identical), guinea pig Y_RNA (81% identical), guinea pig Y_RNA (75% identical). Paralogues in human: RNY4P9 (88% identical), Y_RNA (86% identical), RNY4 (85% identical), Y_RNA (85% identical), RNY4P19 (84% identical), RNY4P6 (84% identical), RNY4P7 (84% identical), RNY4P10 (83% identical), RNY4P14 (83% identical), RNY4P17 (83% identical), RNY4P3 (83% identical), Y_RNA (83% identical), and 92 more.